ESRP1 (epithelial splicing regulatory protein 1)
Diseases named in the same sentence as ESRP1 in open-access papers (continued):
Sharing a sentence is not in itself a finding about the gene and the disease.
non-small cell lung carcinoma (11 papers, 2013 to 2025). A group of at least three distinct histological types of lung cancer, including non-small cell squamous cell carcinoma, adenocarcinoma, and large cell carcinoma. "have shown that ESRP1 expression is significantly increased in precancerous lesions and non-small cell lung cancer (NSCLC) tissues compared to normal lung tissues." (PMID 40046628, 2025). "Higher expression of ESRP1 also results in poor survival in non-small-cell lung cancer and in colorectal carcinoma." (PMID 37752235, 2023). "(A) Heatmap of common AS events between RNAseq data from a previous ESRP1-KD study in human non-small cell lung cancer cells (H358) and our own HCT116 and SW480 EpCAMhi and EpCAMlo RNAseq data." (PMID 36346211, 2022). "(B) CD44 and NUMB exon peak plots relative to the AS analysis of the RNAseq data obtained from a previous ESRP1-KD study in human non-small cell lung cancer cells (H358) and from our own HCT116 and SW480 EpCAMhi/lo analysis." (PMID 36346211, 2022). "Experiments in human non-small cell lung cancer cells have shown that many (but not all) of the splice changes involved in EMT are directly controlled by changing concentrations of ESRP1 and ESRP2." (PMID 37752235, 2023).
colon carcinoma (9 papers, 2013 to 2023). "The ESRP1 gene was also found to be the target of biallelic inactivating mutations in human colon cancers with microsatellite instability." (PMID 28052020, 2017). "However, our finding is in contrast to the high incidence (11 of 23) of primary colon tumors with MSI that include a specific frame-shift mutation in the coding region of the ESRP1 gene." (PMID 27650542, 2016). "This analysis indicated the RBP Epithelial splicing regulatory protein 1 (Esrp1, also known as Rbm35a), first described as a tumor suppressor gene mutated in approximately 50% of primary colon tumors with microsatellite instability, as a protein possibly involved in pluripotency." (PMID 24015231, 2013). "ESRP1 is overexpressed in early stage colon cancer, and ESRP1 downregulation leads to colon cancer cell death." (PMID 37752235, 2023). "ESRP1 downregulation in EpCAMlo colon cancer cells affects alternative splicing (AS) of CD44 and NUMB among a broad spectrum of downstream target genes." (PMID 36346211, 2022). "ZEB1 and ESRP1 differential expression in quasi-mesenchymal and highly metastatic EpCAMlo colon cancer cells." (PMID 36346211, 2022). "Ectopic expression of ESRP1 protein resulted in suppression of tumorigenic potential of LS180 colon cancer cells." (PMID 31440515, 2019). "Overall, in vitro analysis in 4 different colon cancer cell lines indicated a pro-oncogenic role of ESRP1 in CRC, in particular in sustaining anchorage-independent growth and transformation." (PMID 28052020, 2017). "Accordingly, among the top differentially expressed genes (DEGs) between EpCAMlo and EpCAMhi in SW480 and HCT116 colon cancer cells, ESRP1 was found to be downregulated both at the RNA and at the protein level in the quasi-mesenchymal subpopulation where ZEB1 expression is upregulated." (PMID 36346211, 2022). "As for colon cancer, whether ESRP1 regulates AS of CD44 and other target genes downstream of EMT/MET activation during invasion and metastasis is yet poorly understood." (PMID 36346211, 2022). "Likewise, ESRP1 overexpression led to an increase in the CD44v6 and NUMB1/3 isoforms, found in association with the bulk of epithelial colon cancer cells." (PMID 36346211, 2022). "Accordingly, ZEB1 upregulation in EpCAMlo colon cancer cells is invariably accompanied by ESRP1/2 downregulation, and ZEB1hi/ESRP1lo colon cancers, predominantly belonging to the mesenchymal CMS4 subgroup, have a significantly worse survival outcome when compared with ZEB1lo/ESRP1hi patients." (PMID 36346211, 2022). "Also named RBM35A, epithelial splicing regulatory protein 1 (ESRP1) contains three putative RRMs, which are mutational hotspots of primary colon tumors with microsatellite instability (MSI) causing rapid degradation of the mutated transcripts." (PMID 31440515, 2019). "In sum, we confirmed a switch in isoform expression (CD44v6 vs. CD44s and NUMB1/3 vs. NUMB2/4) as a function of ESRP1 and ZEB1 expression in colon cancer." (PMID 36346211, 2022). "Apart from ESRP1, several other RBP-coding genes were found to be differentially expressed between epithelial and quasi-mesenchymal colon cancer cells." (PMID 36346211, 2022). "Fractionation of nuclear and cytoplasmic proteins showed that ESRP1 was mainly located in the cytoplasm in the E14 ES cells, in good agreement with previous reports on LS180 colon carcinoma cells." (PMID 24015231, 2013).
oral squamous cell carcinoma (7 papers, 2017 to 2025). "For example, circUHRF1 enhances oral squamous cell carcinoma (OSCC) tumorigenesis by modulating the expression of epithelial splicing regulatory protein 1 (ESRP1) through the miR-526b-5p/c-Myc/TGF-β1 axis." (PMID 35427215, 2022). "Furthermore, the transcription factor c-Myc which is positively regulated by circUHRF1 promoted the transcription levels of ESRP1 in oral squamous cell carcinoma cells, indicating that circUHRF1 is involved in the upregulation of ESRP1." (PMID 38110955, 2023).
somatotroph adenomas (7 papers, 2017 to 2025). "In somatotroph adenomas, Esrp1 expression was correlated with E-cadherin expression, a negative correlator of EMT, tumor size and tumor invasiveness." (PMID 41111330, 2025). "Changes in EMT markers have been seen in sporadic somatotroph adenomas with lower E-cadherin and ESRP1 expression." (PMID 30867568, 2019). "In a microarray analysis of human somatotroph adenomas, epithelial splicing regulatory protein 1(ESRP1) was differentially expressed in two groups with relatively low or high transcription levels of E-cadherin; the results were validated with RT-PCR and in vivo experiment in GH3 cells." (PMID 30733705, 2019). "Tumor expression of particular genes was found of prognostic/predictive value in acromegaly patients, These genes include basically CDH1 and SSTR2 but also CDKN1B SNAI2, FLNA, ARRB1, SNAI1 RORC ESRP1, and MKI67." (PMID 39497133, 2024).
breast tumor (6 papers, 2016 to 2025). "ESRP1 gene is implicated in cell proliferation and metastasis; thus, down-regulated levels of hsa-miR-337-3p are linked to breast tumor progression." (PMID 39595529, 2024). "Analysis of ERα genome-binding profiles in cell lines and primary breast tumors showed its binding in the proximity of ESRP1 and ESRP2 genes, whose expression is strongly decreased by ERα silencing in hormone-deprived conditions." (PMID 35887187, 2022). "Both TCGA and CPTAC data analysis revealed that ESRP1 gene expression is significantly higher in primary breast tumors than in normal breast tissues." (PMID 34362878, 2021). "Congruent with this observation, the immunoblot analyses exhibited a consistent upregulation of ESRP1 in breast tumors as compared to paired normal tissues (n = 8, P = 0.0002)." (PMID 34362878, 2021). "In our primary breast tumor specimens, correlation between mtDNA content and the expression of ESRP1 (ρ = 0.25, P < 0.001), SNAI1 (ρ = 0.23, P < 0.001) and TGFB1 (ρ = 0.18, P < 0.01) was statistically significant after correction for multiple testing." (PMID 27081694, 2016). "Interestingly, in a previous report, we have demonstrated that ESRP1 expression is shackled in the hypoxic regions of breast tumor, and consequently, hypoxic epithelial cells attain mesenchymal phenotype due to a dramatic re-organization of actin dynamics." (PMID 34362878, 2021). "Notably, similar to ESRP1, E2F1 also gets upregulated in the primary breast tumor as opposed to normal breast tissues." (PMID 34362878, 2021).
pancreatic ductal adenocarcinoma (6 papers, 2016 to 2024). An infiltrating adenocarcinoma that arises from the epithelial cells of the pancreas. "One study confirmed that pancreatic ductal adenocarcinoma patients with high ESRP1 expression have longer survival than those with its low expression." (PMID 39287291, 2024). "Pancreatic ductal adenocarcinoma patients with higher levels of ESRP1 showed longer survival than those with low ESRP1 expression." (PMID 32983230, 2020). "By exploring TCGA and SpliceSeq databases, researchers revealed the aberrant alternative splicing events of DAZAP1, RBM4, ESRP1, and QKI and splicing factors of ESRP1 and RBM5, which contribute to the development of pancreatic ductal adenocarcinoma (PDAC)." (PMID 36713450, 2022).
cervical carcinoma (5 papers, 2019 to 2025). A carcinoma arising from either the exocervical squamous epithelium or the endocervical glandular epithelium. "ESRP1 was shown to induce G1-phase cell cycle arrest and suppress cell proliferation in cervical cancer cells by decreasing cyclin A2 mRNA stability through the direct binding to the 3’ UTR of cyclin A2." (PMID 38110955, 2023). "ESRP1 promoted cell cycle G1-phase arrest and inhibited cell proliferation in cervical carcinoma cells by downregulating cyclin A2 protein levels." (PMID 38110955, 2023). "Epithelial splicing regulatory protein 1 (Esrp1) overexpression induces G1-phase cell cycle arrest by downregulating cyclin A2 expression and inhibits the proliferation of cervical carcinoma cells." (PMID 36880057, 2023). "Herein, we aimed to determine the importance of ESRP1 in cervical carcinoma and to explore the molecular mechanisms whereby it inhibits cell proliferation, clarifying the role of ESRP1 as a potential tumor suppressor gene in cervical cancer." (PMID 31362365, 2019). "We first began by assessing ESRP1 protein levels, as well as those of the widely used proliferative index Ki-67, in 44 archived paraffin-embedded human cervical carcinoma tissue samples via immunohistochemical staining." (PMID 31362365, 2019). "In particular, ESRP1 expression is heavily upregulated in (endo)cervical cancers (~192-fold), but strongly downregulated (~136-fold) in sarcomas." (PMID 30704403, 2019). "This study provides the first evidence that ESRP1 overexpression induces G1-phase cell cycle arrest via reducing the stability of the cyclin A2 mRNA, and inhibits cervical carcinoma cell proliferation." (PMID 31362365, 2019). "The impact of ESRP1 overexpression on the proliferation of cervical cancer cells was examined using a bioluminescence imaging approach." (PMID 31362365, 2019). "This indicates that ESRP1 overexpression can inhibit the growth of HeLa cervical carcinoma cells in vitro." (PMID 31362365, 2019). "The findings suggest that the ESRP1/cyclin A2 regulatory axis may be essential as a regulator of cell proliferation, and may thus represent an attractive target for cervical cancer prevention and treatment." (PMID 31362365, 2019). "To confirm this hypothesis, in the present study, we first examined ESRP1 and Ki-67 expression in 44 human cervical cancer tissue samples, with Ki-67 used as a reliable proliferation marker." (PMID 31362365, 2019). "Taken together, these data suggested that the ESRP1 may induce G1-phase arrest in human cervical cancer cells by downregulating cyclin A2 expression." (PMID 31362365, 2019).
cleft lip (5 papers, 2015 to 2025). Congenital defect in the upper lip where the maxillary prominence fails to merge with the merged medial nasal prominences. "In the mouse, ablation of Esrp1 causes a bilateral cleft lip and cleft palate, and ablation of both Esrp1 and Esrp2 leads to a more severe bilateral cleft lip and palate phenotype." (PMID 41111330, 2025). "For example, the mouse Esrp1 gene is expressed at higher levels than Esrp2, and genetic knockout of mouse Esrp1 causes postnatal death due to cleft lip and palate." (PMID 37752235, 2023). "Finally, ESRP2 human gene variants have been found in cleft lip and palate clinical cohorts, whereas, so far, ESRP1 gene variants have been associated with hearing deficits." (PMID 41111330, 2025). "Notably, loss of Esrp1, an ectodermal specific factor involved in the differential splicing of a number of critical targets including Fgf Receptors, results in cleft lip/palate." (PMID 33013468, 2020). "Previous work showed that Esrp1 null and Esrp1/2 compound null mice exhibit bilateral cleft lip and cleft palate, that and neonates die shortly after birth." (PMID 41111330, 2025). "Taken together, our systematic review indicated the critical role of the IRF6 gene and its downstream genes (GRHL3, KLF17, and ESRP1/2) in the development of cleft lip and palate in zebrafish models." (PMID 38533046, 2024). "In conclusion, this review indicated the critical role of the IRF6 gene and its downstream genes (GRHL3, KLF17, and ESRP1/2) in the development of cleft lip and palate in zebrafish models." (PMID 38533046, 2024). "In contrast, mice with germline KO of Esrp1 exhibited fully penetrant bilateral cleft lip and cleft palate (CL/P), and these mice are neonatal lethal on post natal day 0 (P0) most likely due to orofacial clefting." (PMID 26371508, 2015).
carcinoma in situ (4 papers, 2016 to 2024). "ESRP1 expression is substantially elevated in carcinoma in situ compared to the normal epithelium, whereas it is drastically ablated in cancer cells within hypoxic niches, which promotes epithelial to mesenchymal transition (EMT)." (PMID 34362878, 2021). "In detail, 49 samples of human HNSCC tissues were examined to detect ESRP1/2 in different stages (normal tissue, dysplasia, carcinoma in situ, invasive carcinoma) and a higher expression level of both proteins was detected in dysplasia and carcinoma in situ compared to normal epithelium." (PMID 32957697, 2020). "Such plastic expression also might be important for early colon carcinogenesis as we observed reduced ESRP1 expression in the single carcinoma in situ case #67 of a non-invasive tubulovillous adenoma." (PMID 27650542, 2016).
colitis (4 papers, 2017 to 2025). Inflammation of the colon. "Second, the epithelial splicing regulatory protein 1 (ESRP1) expression was found reduced in samples from IBD patients, and lower ESRP1 levels were associated with impaired intestinal barrier integrity and an increased susceptibility to colitis and CAC." (PMID 39858001, 2025).
gastric tumor (4 papers, 2019 to 2025). "The genes upregulated in the ESRP1-low condition in the gastric tumor tissues were highly enriched in GO terms and KEGG pathways, including focal adhesion, regulation of cell migration, and cell junction assembly." (PMID 36307405, 2022). "ESRP1 amplification occurred in over 60% (209/338 and 57/91) of stomach tumors from cohort #1, and in 15% (7/47) of cohort #2 tumors." (PMID 31881796, 2019). "We first explored CNVs in both FGFR2 and ESRP1 loci and found that these genes were frequently amplified or co-amplified in gastric tumors." (PMID 31881796, 2019). "Our analysis revealed that most gastric tumors presented hypo/demethylation of both FGFR2 and ESRP1 promoters." (PMID 31881796, 2019).
head and neck squamous cell carcinoma (4 papers, 2020 to 2023). A squamous cell carcinoma that arises from any of the following anatomic sites: lip and oral cavity, nasal cavity, paranasal sinuses, pharynx, larynx, and salivary glands. "Higher ESRP1 expression was associated with CD44 variant isoforms, including CD44 isoform 1 (CD44v2-v10), isoform 3 (CD44v8-v10), and CD44v6-v10, in human head and neck squamous cell carcinoma cell lines." (PMID 38106992, 2023).
lung adenocarcinoma (4 papers, 2018 to 2023). A carcinoma that arises from the lung and is characterized by the presence of malignant glandular epithelial cells. "In summary, this article mainly describes the effect of ISG15 in lung adenocarcinoma and the interaction between ESRP1 and ISG15." (PMID 32641707, 2020). "Furthermore, ESRP1 inhibited the invasion and metastasis of lung adenocarcinoma in vivo, and ESRP1 combined with ISG15 synergistically suppressed EMT and lung adenocarcinoma cell invasion." (PMID 38110955, 2023). "Our previous work demonstrated that Epithelial Splicing Regulatory Protein 1 (ESRP1) could inhibit the progression of lung adenocarcinoma (ADC)." (PMID 32641707, 2020). "In our published article, we have elucidated that ISG15 acts as an independent prognostic marker for lung adenocarcinoma (LUAD) and undergoes ISGylation with ESRP1, reducing ESRP1 degradation." (PMID 37217923, 2023). "The transwell assay and wound healing assay results also showed that ESRP1 combined with ISG15 could better inhibit the invasion and metastasis of lung adenocarcinoma cells." (PMID 32641707, 2020).
bladder cancer (3 papers, 2023 to 2024). "ESRP1 inhibited tumor growth and lung metastasis in xenograft mouse model of bladder cancer, and also promoted the polarization of tumor-associated macrophages into anti-tumor phenotype in vivo." (PMID 38110955, 2023). "This suggests that ESRP1 plays a tumor-suppressive role in bladder cancer in part by its effect on macrophage polarization." (PMID 38110955, 2023). "Moreover, another study showed that a reduction in ESRP1 or ESRP2 promoted bladder cancer cell growth and lung metastasis by altering FGFR2 splicing and macrophage polarization." (PMID 39132499, 2024). "Furthermore, ESRP1 reduction promoted tumor growth and lung metastasis of bladder cancer in vivo." (PMID 38110955, 2023).
clear cell renal cell carcinoma (3 papers, 2017 to 2025). "Intriguingly, the cognate circRNA of ESRP1 inhibits EMT clear cell renal cell carcinoma by attuning c-Myc activity." (PMID 39550559, 2024). "Moreover, ESRP1 is involved in the biogenesis of circ-TNPO3, which significantly suppresses the proliferation and migration of clear cell renal cell carcinoma cells." (PMID 39550559, 2024).
female infertility (3 papers, 2022 to 2024). Diminished or absent ability of a female to achieve conception. "The gene ESRP1, which is significantly overexpressed in relation to infection and vaccination in SAT, is a crucial component of the spliceosome, and the loss of ESRP1 leads to female infertility due to oocyte development dysregulation." (PMID 38474155, 2024). "Depletion of ESRP1 in mouse oocytes results in maturation defects and female infertility." (PMID 38587639, 2024). "For example, ESRP1 is involved in the AS programming of oocyte mRNA processing and the ESRP1 deletion-induced pre-mRNA splicing changes in spindle organization-related genes that lead to female infertility." (PMID 35154017, 2022).
lymph node metastasis (3 papers, 2011 to 2023). "Further analysis revealed that ESRP1 expression was negatively correlated with lymph node metastasis rate (LNR), an important clinical indicator reflecting lymph node metastasis." (PMID 38114495, 2023). "Both, high ESRP1 and high ESRP2 staining were significantly associated with adverse tumor features, including advanced tumor stage, high Gleason grade, presence of lymph node metastasis (p < 0.0001 each), and high early PSA recurrence (p < 0.0001 each)." (PMID 33339518, 2020).